CELSR2 (cadherin EGF LAG seven-pass G-type receptor 2)
Diseases named in the same sentence as CELSR2 in open-access papers (continued):
Sharing a sentence is not in itself a finding about the gene and the disease.
glioma (1 paper, 2025). A benign or malignant brain and spinal cord tumor that arises from glial cells (astrocytes, oligodendrocytes, ependymal cells). "In cultured glioma cells, CELSR2 knockdown reduced proliferation and caused cell cycle arrest, which was further supported by proteomic analysis." (PMID 41184253, 2025). "Immunohistochemical studies of clinical samples confirmed that glioma development was associated with CELSR2 expression elevation." (PMID 41184253, 2025). "The results suggest that CELSR2 is associated with the development of glioma, and inhibiting CELSR2 may be a potential strategy for glioma treatment." (PMID 41184253, 2025). "First, further expansion of the clinical sample cohort is required to elucidate the association between CELSR2 expression levels and glioma pathological subtypes, as well as patient prognosis, which is essential for the development of personalized therapeutic strategies." (PMID 41184253, 2025). "Immunohistochemical staining showed an increased expression of CELSR2 proteins in Grade 2 and Grade 3 glioma tissues." (PMID 41184253, 2025). "Consistently, CELSR2 mRNA levels were markedly elevated in low-grade gliomas (Grade 1 and Grade 2) and high-grade gliomas (Grade 3 and Grade 4) relative to normal brain tissue." (PMID 41184253, 2025). "The expression level of CELSR2 mRNA was significantly higher in glioma tissues than that in para-tumor tissues." (PMID 41184253, 2025). "Collectively, our studies suggest that CELSR2 represents a promising molecular target for the clinical treatment of glioma." (PMID 41184253, 2025). "CELSR2 expression was further evaluated in glioma tissues from clinical patients and glioma cell lines." (PMID 41184253, 2025). "We further evaluated the impact of CELSR2 inhibition on glioma growth in the brain microenvironment using an orthotopic glioma model." (PMID 41184253, 2025). "In conclusion, our study demonstrates for the first time that CELSR2 promotes human glioma growth via the WNT3A/β-catenin pathway and administration of MNPs-loaded CELSR2-siRNA is a promising therapeutic strategy for gliomas." (PMID 41184253, 2025). "We recently demonstrated that Celsr2 is essential for injury-induced responses and functions of astrocytes, while its role in the development and treatment of gliomas remains unexplored." (PMID 41184253, 2025). "Our study demonstrates that GSK-3β and β-catenin are the downstream signaling partners of CELSR2 in regulating human glioma growth." (PMID 41184253, 2025). "Our findings suggest that CELSR2 acts as one possible receptor of WNT3A ligand to influence human glioma growth." (PMID 41184253, 2025). "In this study, an increase of CELSR2 expression was identified in patient glioma samples and glioma cell lines, and higher levels of CELSR2 correlate with poorer patient survival as indicated by TCGA data." (PMID 41184253, 2025). "WNT3A efficiently enhanced the proliferation of glioma cells and activated the downstream signaling, which were significantly compromised by CELSR2 knockdown." (PMID 41184253, 2025). "Simultaneously, WNT3A-induced activation of the GSK-3β/β-catenin signaling and enhancement of cell cycle was significantly compromised in cultured CELSR2 KD glioma cells." (PMID 41184253, 2025). "Our analysis of the clinical sample database demonstrates that CELSR2 expression is significantly upregulated in a substantial subset of glioma specimens." (PMID 41184253, 2025). "In conjunction with findings from our animal model studies, these data confirm that suppression of CELSR2 expression markedly inhibits glioma growth." (PMID 41184253, 2025). "The results are attributed to increasing glial cells in glioma tissues and CELSR2 involvement in the glioma development." (PMID 41184253, 2025).
glioma (continued). "In patients with primary and recurrent glioma, the survival probability was negatively correlated with CELSR2 expression in the glioma tissues: patients with higher CELSR2 mRNA levels in the glioma tissues showed a shorter survival time." (PMID 41184253, 2025). "In this study, CELSR2 mRNA was also identified in the normal human astrocyte line (CP-H122), whereas its level was significantly increased in the human glioma cell lines (U87 MG and U251)." (PMID 41184253, 2025). "In cultured glioma cells, CELSR2 was knocked down by CELSR2-shRNA and the effects on glioma growth were investigated both in vitro and in vivo." (PMID 41184253, 2025). "In conclusion, CELSR2 positively regulates glioma development through WNT3A/β-catenin signaling and inhibiting CESLR2 is a novel therapeutic strategy for gliomas." (PMID 41184253, 2025). "From these findings, we propose that CELSR2 elevation in gliomas (cultured cells and patient samples) is not only because of an increase of proliferating glial cells but also due to CELSR2-regualting proliferation." (PMID 41184253, 2025). "To confirm this finding, we collected glioma and para-tumor tissues from clinical patients (Grade 2 and Grade 3 gliomas) and studied CELSR2 expression using RT-qPCR." (PMID 41184253, 2025). "Taking together, we identify a novel signaling pathway-WNT3A/CELSR2/GSK-3β/β-catenin in the development of gliomas." (PMID 41184253, 2025). "To clarify the role of CELSR2, we knocked down CELSR2 in the glioma cell line (U87 MG) and primary glioma cells (Grade 3) using lentiviral vectors expressing CELSR2-shRNA." (PMID 41184253, 2025). "Strikingly, CELSR2 KD led to a significant decrease in the S phase and a concurrent increase in the G0/G1 phase in U87 MG cells, and in Grade 3 primary glioma cells, CELSR2 KD led to a significant decrease both in the S and G2/M phase and a concurrent increase in the G0/G1 phase." (PMID 41184253, 2025). "To test whether CELSR2 is also involved in the development of glioma, we first studied the expression of CELSR2 in the glioma tissues from the clinical patients." (PMID 41184253, 2025). "Immunostaining showed that CELSR2 was positive in GFAP-positive astrocytes of both CP-H122 and U87 MG cell lines, but a rare detectable CELSR2-positive signal was found in the CELSR2-shRNA treated U87 MG cell lines and CELSR2-shRNA treated Grade 3 primary glioma cells." (PMID 41184253, 2025). "Similarly, CELSR2 mRNA was significantly upregulated in two glioma cell lines (U87 MG and U251) compared to the normal astrocyte line (CP-H122)." (PMID 41184253, 2025). "Our present study demonstrates that CELSR2 is a potential molecular target for glioma therapy, and inhibiting CELSR2 function may become an important intervention option combined with surgical treatment." (PMID 41184253, 2025). "Glioma cell culture study showed that CELSR2 KD induced an upregulation of total GSK-3β (phosphorylated protein decrease) and phosphorylated β-catenin (total protein decrease), and a decrease of TCF/LEF activity, showing an inactive state of the Wnt-β-catenin signaling." (PMID 41184253, 2025). "Since most gliomas originate from glial cells, we hypothesized that CELSR2 might be involved in the development and treatment of glioma." (PMID 41184253, 2025). "To further confirm whether CELSR2 is involved in the regulation of Wnt/β-catenin signaling pathway to influence proliferation and cell cycle of glioma cells, we used the GSK-3β inhibitor TWS119 to activate Wnt/β-catenin." (PMID 41184253, 2025). "Notably, CELSR2 mRNA expression was significantly higher in Grade 2, Grade 3 and recurrent Grade 4 gliomas when compared to the normal control group." (PMID 41184253, 2025). "The results suggest that CELSR2 KD compromises WNT3A induced glioma proliferation." (PMID 41184253, 2025). "Thus, CELSR2-siRNA and MNPs-loaded CELSR2-siRNA similarly knock down CELSR2 expression, decrease proliferation, and disturb cell cycle of cultured glioma cells." (PMID 41184253, 2025).
glioma (continued). "In CELSR2 KD glioma cells, suppressing GSK-3β activation using inhibitors induced downregulation of phosphorylated β-catenin and upregulation of unphosphorylated β-catenin which subsequently activated nuclear transcription and cell proliferation as shown by EdU labeling and cell cycle analysis." (PMID 41184253, 2025). "Combined with our study, CELSR2 is a novel potential therapeutic target for gliomas, and CELSR2 silencing disrupts the Wnt/β-catenin pathway and induces cell cycle arrest and tumor proliferation inhibition, which is considered as one of the therapeutic strategies in cancer treatment." (PMID 41184253, 2025). "To address our hypothesis, we first analyzed the online TCGA data related to glioma patients to reveal CELSR2 expression in glioma tissues and its correlation with patient overall survival (OS)." (PMID 41184253, 2025). "Thus, CELSR2 regulates the proliferation and cell cycle of glioma cells possibly through the Wnt/β-catenin signaling pathway." (PMID 41184253, 2025). "Thus, CELSR2 KD-induced proliferation reduction and cell cycle arrest of glioma cells could be reversed by activating the downstream signaling of the Wnt/β-catenin pathway." (PMID 41184253, 2025). "Thus, CELSR2 is an important biomarker indicating glioma development." (PMID 41184253, 2025). "We then asked whether inactivating CELSR2 could be a therapeutic strategy for glioma." (PMID 41184253, 2025). "Meanwhile, although CELSR2 expression was significantly upregulated in Grade 2, Grade 3 and recurrent Grade 4 gliomas, a significantly shorter survival time was only observed in patients with elevated CELSR2 mRNA levels specifically in Grade 3 gliomas and recurrent Grade 4 gliomas." (PMID 41184253, 2025). "Our data demonstrate that CELSR2 promotes glioma growth through WNT3A/β-catenin signaling and inhibiting CELSR2 is a novel strategy for glioma therapy." (PMID 41184253, 2025). "CELSR1-3 plays an important role in the epithelium and nervous system via the WNT signaling pathway, but the effect of CELSR2 on glioma growth through the regulation of the WNT pathway has not been reported in the relevant literature." (PMID 41184253, 2025). "In line with this, we found a negative correlation between CELSR2 expression and OS of patients with gliomas." (PMID 41184253, 2025). "After CELSR2 was knocked down by CELSR2-shRNA, proliferation of glioma growth was significantly downregulated as shown by EDU labelling, and cell cycle of growing glioma was arrested as shown by an increase of G0/G1 ratio and a decrease of S phase." (PMID 41184253, 2025). "To further investigate the effect of inhibiting CELSR2 on glioma growth in vivo, we subcutaneously inoculated U87 MG cells with or without CELSR2-shRNA transfection (CELSR2-KD group or control group) in nude mice." (PMID 41184253, 2025). "CELSR2 knockdown inhibited Wnt/β-catenin signaling, and the effect could be reversed by activating β-catenin using GSK-3β inhibitor in glioma cells." (PMID 41184253, 2025). "However, the enhanced glioma proliferation induced by WNT3A, but not by WNT5A or WNT1, was diminished by CELSR2 silencing." (PMID 41184253, 2025). "To further explore potential molecular mechanisms of CELSR2 KD-induced proliferation inhibition in glioma cells, we performed data-independent acquisition (DIA) proteomics with protein extracts from cultured U87 MG cells transfected without (control) or with CELSR2-shRNA (CELSR2 KD)." (PMID 41184253, 2025).
glucocorticoid resistance (1 paper, 2022). "Genome-wide orthogonal validation identified CELSR2 (Cadherin EGF LAG Seven-Pass G-Type Receptor 2) as a key mediator of glucocorticoid resistance that was strengthened by CELSR2 knockdown." (PMID 35761157, 2022).
idiopathic scoliosis (1 paper, 2017). A scoliosis with no known cause. "Our analysis highlighted a rare non-synonymous variant in CELSR2 as a plausible idiopathic scoliosis risk variant." (PMID 29240829, 2017). "The two common variants in CELSR2 that showed significant association to idiopathic scoliosis in the Swedish-Danish population, rs6698843 and rs2281894, were further tested for association in two additional case-control datasets." (PMID 29240829, 2017). "This further argues for the importance of the GAIN domains and supports our idea that any mutations abolishing their function (in ADGRG6 or CELSR2) would likely lead to more severe phenotypes than idiopathic scoliosis." (PMID 29240829, 2017). "In order to further understand the possible importance of CELSR2 in idiopathic scoliosis, we genotyped common variants within CELSR2 and the related genes CELSR1 and 3, in a large independent case-control cohort." (PMID 29240829, 2017). "By linkage analysis and exome sequencing of a family with a high burden of idiopathic scoliosis we identified a rare missense mutation in the highly conserved CELSR2 gene." (PMID 29240829, 2017). "This phenotype is obviously more severe than idiopathic scoliosis and supports the notion that a drastic change in the function of CELSR2, e.g. a gain-of-function due to the mutation, would likely be lethal or cause a more severe phenotype than idiopathic scoliosis." (PMID 29240829, 2017). "The identification of CELSR2 and understanding how it might contribute to the risk of idiopathic scoliosis may shed further light on the pathways and mechanisms involved in the pathogenesis of idiopathic scoliosis." (PMID 29240829, 2017). "In conclusion, we have identified CELSR2 as a putative novel risk gene idiopathic scoliosis, and we hypothesise that this effect may be mediated through a disruption of the auto-proteolytic mechanism of the GAIN domain in the CELSR2." (PMID 29240829, 2017).
liver cirrhosis (1 paper, 2020). "On univariate analysis, AFP level, liver cirrhosis and CELSR2 expression were identified as significant factors of recurrence-free survival (RFS)." (PMID 32293343, 2020). "Similarly, based on multivariate analysis, patient age, tumor size, liver cirrhosis and CELSR2 expression were significantly related to overall survival in HCC patients." (PMID 32293343, 2020).
liver fibrosis (1 paper, 2024). "Notably, Celsr2 had a missense variant in the DO population and GWAS data show that Celsr2 is strongly associated with liver fibrosis in individuals with high alcohol intake and with interaction terms between alcohol consumption and both LDL and HDL cholesterol levels." (PMID 38951586, 2024).
nonalcoholic fatty liver disease (1 paper, 2023). "The gene CELSR2, known for its involvement in cell adhesion and signaling, plays a crucial role in suppressing lipid accumulation and thus mitigating nonalcoholic fatty liver disease (NAFLD), as reported in prior research." (PMID 37958793, 2023).
osteoporosis (1 paper, 2024). A condition of reduced bone mass, with decreased cortical thickness and a decrease in the number and size of the trabeculae of cancellous bone (but normal chemical composition), resulting in increased fracture incidence. "CELSR2, traditionally linked with neuronal development, has also been found to play a role in non-neurological diseases and could be associated with osteoporosis through its involvement in lipid metabolism, endoplasmic reticulum stress, and reactive oxygen species (ROS)." (PMID 39526243, 2024).
prostate carcinoma (1 paper, 2020). A carcinoma that arises from epithelial cells of the prostate gland. "In prostate cancer, methylation of CELSR2 has been shown to play an important role in carcinogenesis and tumor progression." (PMID 32293343, 2020). "In addition, methylation of CELSR2 has been shown to play an important role in carcinogenesis and tumor progression in prostate cancer." (PMID 32293343, 2020).
rapidly progressive glomerulonephritis (1 paper, 2021). Inflammation of the glomeruli that is characterized by a rapid loss in renal function with glomerular crescent formation observed on biopsy; it is often seen in patients with concomitant autoimmune disease, like Goodpasture's syndrome or systemic lupus erythematosus. "The NTN model mirrors human rapidly progressive glomerulonephritis (RPGN), and recently, transcripts for VANGL1, VANGL2, CELSR2, DVL2, DVL3, PK1, and PK2 were found to be significantly upregulated in two independents cohorts of RPGN biopsies compared to living kidney donor controls." (PMID 33716764, 2021).
tobacco-use disorder (1 paper, 2017). "Gene-disease association shows SORCS1, SKAP2, and CELSR2 genes are related with genetic susceptibility, and genes SORCS1 and PCDH10 are related with tobacco-use disorder." (PMID 28079101, 2017).
tumor (6 papers, 2018 to 2025). "After one month of inoculation, tumor tissues were collected, revealing a significant decrease in tumor volume and weight in the CELSR2-KD group compared to the control group." (PMID 41184253, 2025). "In the one-month growing tumor tissues, immunohistochemical staining revealed a significant downregulation of CELSR2 in the CELSR2-KD group compared to the control group." (PMID 41184253, 2025). "Immunohistochemical staining revealed a significant downregulation of CELSR2 immunoreactivities in tumor tissues in the siRNA MNPs group compared to the control and MNPs groups." (PMID 41184253, 2025). "We also identified two genes with significantly higher prevalence in the VTT tissues compared with the matched primary tumor tissues, including CELSR2 (30.43 vs. 4.00%, p < 0.05) and TET2 (17.39 vs. 0, p < 0.05)." (PMID 34249685, 2021). "Additionally, we found a significant upregulation of p-β-catenin and GSK-3β, and a significant downregulation of CELSR2, β-catenin, p-GSK-3β and cyclinD1 in the CELSR2-KD group compared to the control group in the tumor nodule, as assessed by RT-qPCR." (PMID 41184253, 2025). "Finally, we analyzed the relationship between mRNA expression and tumor grade or stage and found that the mRNA expression level of CELSR2 was positively correlated with tumor stage in HCC patients, which indicated high CELSR2 expression was probably associated with poor clinical characteristics." (PMID 32293343, 2020). "Proteins were extracted from tumor nodules and followed by Western blots, showing upregulation of p-β-catenin and GSK-3β and downregulation of CELSR2 and β-catenin in the siRNA MNPs group compared to the control group." (PMID 41184253, 2025). "Considering the roles of CELSR2 in other tumors, we hypothesized this study on the function and mechanism of CELSR2 in HCC, which was urgently needed to better elucidate the occurrence and progression of this tumor." (PMID 32293343, 2020). "The gene expression of CELSR2 in liver tissue was lower than that in other normal tissues (liver/other normal: logFC = − 2.10), and CELSR2 expression in HCC was lower than that in other tumor tissues (HCC/all tumor: logFC = − 2.16), which were consistent with results in the HPA." (PMID 32293343, 2020). "Moreover, the genetic alteration rate of CELSR2 gene in HCC can reach 8%, and these alterations would deeply influence its neighboring genes, then jointly affecting the occurrence and development of tumor through cell adhesion and numerous common carcinogenic pathways." (PMID 32293343, 2020).
cancer (5 papers, 2019 to 2025). A tumor composed of atypical neoplastic, often pleomorphic cells that invade other tissues. "We first detected the expression of CELSR2 at both the mRNA and protein levels in normal human organs and common cancers using the HPA database." (PMID 32293343, 2020). "As both CELSR2 and ADAM17 seem to have growth‐stimulating functions, the loss‐of‐function mutations are less likely candidates for cancer predisposition." (PMID 30809968, 2019). "CELSR2 KD resulted in a significant downregulation of cyclin D1, which is an important regulator of cell cycle and plays a central role in the pathogenesis of cancer." (PMID 41184253, 2025).